DACH1 (dachshund family transcription factor 1)
Diseases named in the same sentence as DACH1 in open-access papers (continued):
Sharing a sentence is not in itself a finding about the gene and the disease.
esophageal squamous cell carcinoma (1 paper, 2020). Esophageal squamous cell carcinoma (ESCC) is a type of esophageal carcinoma (EC) that can affect any part of the esophagus, but is usually located in the upper or middle third. "Metformin reduced CXCL1 secretion in esophageal squamous cell carcinoma (ESCC) cells through enhancing AMPK phosphorylation and inducing Dachshund homolog 1 (DACH1) expression." (PMID 33613512, 2020).
focal segmental glomerulosclerosis (1 paper, 2024). A renal disorder characterized by sclerotic lesions in the glomeruli. "In contrast, among our podocyte-specific Dach1 KO mice, a significant portion exhibited focal segmental glomerulosclerosis (FSGS) at baseline despite a low rate of Dach1 deletion." (PMID 38805434, 2024).
heart failure (1 paper, 2020). Inability of the heart to pump blood at an adequate rate to meet tissue metabolic requirements. "The lncRNA DACH1 is reported to directly bind and increase ubiquitination of SERCA2 in heart failure, thereby enhancing SERCA protein degradation, decreasing SR Ca2+ re-uptake, and inhibiting cardiac contractility." (PMID 33202832, 2020).
Hepatic hemangioma (1 paper, 2015). A congenital vascular malformation in the liver composed of masses of blood vessels that are atypical or irregular in arrangement and size. "Tissues from hepatic hemangioma patients were DACH1 negative, indicating DACH1 specifically expressed in hepatocyte." (PMID 25940701, 2015).
Hyperinsulinemia (1 paper, 2023). An increased concentration of insulin in the blood. "Liver-specific silencing of DACH1 improves hepatocyte insulin signaling, and protects against hyperinsulinemia, which suggested that DACH1 was also involved in the metabolism of hepatocytes." (PMID 36750914, 2023).
hypopharyngeal squamous cell carcinoma (1 paper, 2024). "In hypopharyngeal squamous cell carcinoma, the crosstalk between cancer cells and TAMs mediates tumor progression through the transcription factor DACH1, which acts as a negative transcriptional regulator of IGF1." (PMID 38892104, 2024).
large cell carcinoma (1 paper, 2015). A malignant epithelial neoplasm composed of large, atypical cells. "As previously reported, DACH1 was highly expressed in the nuclei of lung epithelial cells, but dramatically reduced in adenocarcinoma, squamous carcinoma, and large cell carcinoma." (PMID 25788272, 2015).
laryngeal carcinoma (1 paper, 2018). Carcinoma that arises from the laryngeal epithelium. "Smoking and alcohol consumption were risk factors of laryngeal carcinoma, and DACH1 increased the risk of laryngeal carcinoma which is consistent with other study." (PMID 30261897, 2018).
membranous nephropathy (1 paper, 2023). "DACH1 expression decreased in glomerulus and renal tubule of membranous nephropathy (MN) (P < 0.05), while TCF21 expression increased in MN, especially in the renal tubule cells (P < 0.05)." (PMID 36875100, 2023).
metastatic cancer (1 paper, 2022). A carcinoma which has spread from the original site of growth to another anatomic site. "DACH1 encodes a chromatin-related protein, and its expression is lost in some forms of metastatic cancer and is associated with poor prognosis." (PMID 35513781, 2022).
oral squamous cell carcinomas (1 paper, 2015). "In the first stage, 16 oral squamous cell carcinoma cell lines were screened for the methylation of DACH1, DKK1, LKB1, PPP2R2B, RUNX3, SFRP2, and WIF-1 using methylation-specific PCR." (PMID 25487617, 2015). "We report, for the first time, that DACH1 undergoes methylation in oral squamous cell carcinomas." (PMID 25487617, 2015). "The methylation of DACH1, DKK1, LKB1, PPP2R2B, RUNX3, SFRP2, and WIF-1 was analyzed in 16 oral squamous cell carcinoma cell lines using the methylation-specific polymerase chain reaction." (PMID 25487617, 2015). "Based on these results, we identified DACH1, DKK1, and WIF-1 as potential epimarkers in OSCC and further analyzed their methylation in a group of oral squamous cell carcinoma patients." (PMID 25487617, 2015).
oropharyngeal squamous cell carcinomas (1 paper, 2015). "In summary, our current study showed that DACH1, DKK1, and WIF-1 are methylated in oral and oropharyngeal squamous cell carcinomas." (PMID 25487617, 2015).
osteoporosis (1 paper, 2024). A condition of reduced bone mass, with decreased cortical thickness and a decrease in the number and size of the trabeculae of cancellous bone (but normal chemical composition), resulting in increased fracture incidence. "While the DACH1 genetic data and the treatment with anti-osteoporosis drugs suggest that type R capillaries have a positive influence on osteogenesis and bone mass, the emergence of these vessels in ageing cortical bone argues for a potential role in bone loss." (PMID 39528700, 2024).
phaeochromocytoma (1 paper, 2015). "DACH1 protein expression in the normal adrenal glands adjacent to APA or phaeochromocytoma was highly selective for ZG compared with other adrenal zones, with the staining being confined to nuclei." (PMID 25776071, 2015).
prediabetes (1 paper, 2014). "We found reduced expression of DACH1 in PBMC from subjects with YOD and association of the T allele of rs1408888 with YOD, prediabetes and CVD." (PMID 24465431, 2014). "The T allele of rs1408888 of DACH1 was associated with YOD, prediabetes and CVD in Chinese." (PMID 24465431, 2014).
prostate hyperplasia (1 paper, 2024). "Our research revealed that DACH1 is primarily linked to cytokines and inflammatory responses in prostatic hyperplasia samples." (PMID 39703506, 2024). "ROC curves were then used to assess the predictive potential of these key gene markers in prostate enlargement, revealing AUC values of 0.885, 0.874, 0.885, and 0.874 for DACH1, CACNA1D, STARD13 and RUNDC3B, respectively." (PMID 39703506, 2024). "To delve deeper into the potential mechanisms of DACH1, CACNA1D, STARD13, and RUNDC3B in regulating prostate hyperplasia, we stratified prostate hyperplasia samples according to the levels of expression of these genes and conducted GSEA." (PMID 39703506, 2024).
renal failure (1 paper, 2023). "Moreover, global knockouts of Dach1 in mice lead to early postnatal death, and kidney hypoplasia suggesting global Dach1-KO mice die from renal failure." (PMID 36659918, 2023).
supraglottic tumor (1 paper, 2018). "In addition, it was found that lower expression of DACH1 was closely correlated with supraglottic tumor, lymph node metastases, T3–4 stage and advanced clinical stage." (PMID 30261897, 2018).
Thrombocytopenia (1 paper, 2024). A reduction in the number of circulating thrombocytes. "Our findings unveiled a decreasing trend in DACH1 gene mRNA levels among patients with thrombocytopenia when compared with healthy donors." (PMID 38542074, 2024). "In summary, our findings shed light on one of the molecular mechanisms behind LT-induced thrombocytopenia and unveil a previously unknown role for DACH1 in megakaryopoiesis." (PMID 38542074, 2024). "Given the critical role of the DACH1 gene in megakaryopoiesis, our research was driven by curiosity to explore its involvement in clinical megakaryopoiesis defects, particularly in patients with thrombocytopenia, given its fundamental role in normal megakaryopoiesis." (PMID 38542074, 2024). "Furthermore, we observed an upregulation of DACH1 during in vitro differentiation of CD34–megakaryocytes and downregulation of DACH1 in patients with thrombocytopenia." (PMID 38542074, 2024).
thrombosis (1 paper, 2020). "Consistent with the hypothesis, targeting hepatocyte DACH1 (HC-DACH1–KO mice) increased liver Plat mRNA, plasma tPA concentration and activity, and time to occlusive carotid thrombosis." (PMID 32657780, 2020).
thyroid cancer (1 paper, 2024). "Furthermore, we evaluated the clinicopathological relevance of the miR‐31‐CEBPA/DACH1 axis in thyroid cancer." (PMID 38797942, 2024). "Of note, CEBPA and DACH1 have been reported as tumour suppressors in different types of cancers, while their function in thyroid cancer is currently unknown." (PMID 38797942, 2024). "Thus, CEBPA and DACH1 could be direct target genes of miR‐31 during thyroid cancer development." (PMID 38797942, 2024).
tumor (76 papers, 2012 to 2025). "This was aligning with previous findings linking the loss of DACH1 expression to tumor development and poor prognosis." (PMID 40370966, 2025). "Overall, these results underscore the close association between DACH1 protein expression and tumor proliferation, invasiveness, and patient prognosis in CRC, while DACH1 mRNA levels did not accurately reflect this link." (PMID 40389405, 2025). "In CRC, previous studies suggest that the loss of DACH1 expression is associated with tumor progression." (PMID 40370966, 2025). "Higher DNMT1 expression and lower DACH1 expression were associated with poorer clinical outcomes, including worse tumor differentiation, lymphatic metastasis, and advanced tumor stages." (PMID 40370966, 2025). "In this model, the loss of DACH1 is tumor cells enhances the secretion of IGF1, which in turn binds and activates the IGF1R and downstream signaling in TAMs." (PMID 38892104, 2024). "We found that CEBPA KO and DACH1 KO effectively reversed the reduced tumour cell functions caused by miR‐31 KO." (PMID 38797942, 2024). "The ANOVA (Analysis of Variance) and the t-test were used to analyze the relationship between DACH1 expression and tumor grade, patient age, MGMT methylation status, and IDH mutation status." (PMID 36959804, 2023). "DACH1 (dachshund family transcription factor 1) is a crucial cytokine linked to tumor development, and is associated with the growth of many different malignant tumor cells." (PMID 37766305, 2023). "By informatics analysis, we identified three tumor suppressor genes: DACH1, PCDH10 and SMAD4, all of which were negatively associated with FOXM1 and validated as functionally relevant targets of miR-552." (PMID 33867818, 2021). "DACH1 was identified as a suppressor of the progression of various neoplasms and its downregulation is associated with a poor prognosis." (PMID 34390367, 2021). "Given DACH1’s control of transcription regulation and the cell cycle, we then evaluated its effect on tumor mutation burden and microsatellite instability." (PMID 33378353, 2020). "DACH1 mutations were associated with increased tumor mutation count in both TCGA (median 65 vs. 8972, p-value = 7.35E-09) and our Kentucky population (490 vs. 2160, p-value = 6.0E-04)." (PMID 33378353, 2020). "Our primary objective was to determine the frequency of DACH1 mutations in our population and their association with other tumor suppressor genes, tumor mutation burden, microsatellite instability, and clinical risk factors." (PMID 33378353, 2020). "DACH1 mutated patients have a higher tumor mutation burden compared to DACH1 wild-type (24 vs. 6.02, p-value = 4.29E-05)." (PMID 33378353, 2020). "DACH1, implicated in the suppression of tumor growth, is downregulated in human malignancies, such as LC." (PMID 30364292, 2018). "Whole-genome and transcriptome sequencing of NSCLC tumor and normal tissues identified mutation and copy number loss of DACH1." (PMID 29636079, 2018). "Taken together, our study was consistent with a previous study that DACH1 was negatively correlated with tumor progression, whereas high CXCL8 expression was associated with unfavorable prognosis of NSCLC patients." (PMID 29636079, 2018). "DACH1 has been shown to involve in regulating cell-cycle and be associated with proliferation in most of tumour cell." (PMID 27888806, 2016). "DACH1 encodes a chromatin-associated protein that regulates gene expression and cell fate determination during development, and also functions as a tumor suppressor gene." (PMID 27993161, 2016). "Nuclear distribution of DACH1 has been observed in other tissues with loss associated with apparent decline in tumor suppression." (PMID 25776071, 2015). "Our investigation further proved decreased DACH1 expression linked with lower tumor grading as well as staging." (PMID 25940701, 2015).
tumor (continued). "Considering the multiple functions of CXCL5 in terms of proliferation, invasion, inflamation and tumor-environment interaction, our results further enrich the understanding of the underlying mechanism by which DACH1 acts as a tumor suppressor." (PMID 25788272, 2015). "A semi-quantitive analysis revealed progressive loss of DACH1 expression in relation to tumor stage and histological grade." (PMID 25788272, 2015). "Loss/reduction of DACH1 expression was significantly associated with promoter region hypermethylation in the tumours (P < 0.01)." (PMID 24912879, 2014). "DACH1 methylation was associated with poor differentiation (P<0.05) and late tumor stage (P<0.05) significantly." (PMID 24743895, 2014). "However, tumor differentiation, lymphatic metastasis, and tumor stage were significantly associated with DACH1 and DNMT1 expression." (PMID 40370966, 2025). "The expression of DACH1 is deficient or down-regulated in multiple carcinomas, suggesting that DACH1 might be a new tumor suppressor." (PMID 34772908, 2021). "CHEK2 and DACH1 is a tumour suppressor, however amplification of its mutated form may cause dominant-negative effect." (PMID 31041889, 2019). "DACH1, a gene associated with tumor progression, was further analyzed." (PMID 25776071, 2015). "It suggested that the loss of DACH1 led to a growth advantage of tumor cells." (PMID 25322986, 2014). "DACH1 methylation was associated with poor differentiation (P<0.05) and late tumor stage (P<0.05)." (PMID 24743895, 2014). "Clinical parameters further highlighted the association of DACH1 and DNMT1 expression with tumor differentiation, lymphatic metastasis, and tumor stage." (PMID 40370966, 2025). "Both in vivo and in vitro proliferation experiments emphasized the central role of DACH1 in USP7-mediated tumor proliferation." (PMID 40389405, 2025). "Our research focused on investigating the acetylation modifications of the DACH1 protein and its implications for tumor biology." (PMID 40389405, 2025). "Emerging evidence has identified DACH1 as a tumor suppressor gene involved in regulating key processes such as cell proliferation, apoptosis, and invasion across various cancers including breast, prostate, and lung cancers." (PMID 40370966, 2025). "USP7 was identified as a deubiquitinase that stabilizes DACH1, enhancing its tumor-promoting activities." (PMID 40389405, 2025). "The inverse correlation between DNMT1 and DACH1 expression highlighted the potential role of DNMT1 in silencing tumor suppressor genes DACH1 through epigenetic mechanisms." (PMID 40370966, 2025). "Strikingly, further KO of CEBPA rescued tumour growth, even further promoted tumour growth greater than control, and DACH1 KO also performed similarly." (PMID 38797942, 2024). "MiR‐31 represses tumour suppressors DACH1 and CEBPA, which otherwise direct the CD9, CD82 and AXIN1 expression." (PMID 38797942, 2024). "The alterations in the sensitivity of tumor cells to temozolomide were also observed after DACH1 was silenced." (PMID 36959804, 2023). "The xenograft models indicated that DACH1 expression significantly retarded tumor growth and downregulated S100A8/A9 protein abundance." (PMID 38093319, 2023). "The results of the “estimate” package analysis showed that the DACH1 low expression group had higher StromalScore, ImmuneScore, and ESTIMATEScore, as well as lower tumor purity, indicating that downregulating DACH1 can promote immune cell infiltration." (PMID 36959804, 2023). "In the process of functional prediction of model signature genes, we found that DACH1 is closely associated with transcriptional misregulation in cancer and TGF-beta, both of which are crucial for the development of tumor treatment resistance." (PMID 36959804, 2023). "The imbalance between the tumor-suppressor function of DACH1 and the oncogenic effect of SIX/EYA not only accelerates cell cycle disorder but also decreases apoptosis, providing the basis for tumorigenesis." (PMID 36750914, 2023).
tumor (continued). "The results showed that sustained DACH1 expression significantly retarded tumor growth and decreased tumor weight." (PMID 38093319, 2023). "We assessed DACH1 DNA methylation and RNAseq expression data from firebrowse.org, for the n = 333 primary tumor samples and n = 43 adjacent tissue normal samples in the cBioPortal TCGA 2015 cohort." (PMID 37095257, 2023). "In general, DACH1 is down-regulated as a tumor suppressor, while SIX and EYA are up-regulated in tumors, which promotes tumorigenesis and tumor progression." (PMID 36750914, 2023). "DACH1 is not only involved in tumor progression but also participates in CKD, cardiovascular diseases, and bilateral cystic renal dysplasia." (PMID 36750914, 2023). "5-Aza-2'-deoxyazacytidine, a demethylating agent, reactivated DACH1 expression, which would manipulate for tumor therapy." (PMID 36750914, 2023). "Transcriptional misregulation in cancer is an important player in regulating tumor development, metastasis, and chemotherapy resistance, and it was found to be closely related to DACH1 in the functional prediction." (PMID 36959804, 2023). "Recently, several studies have confirmed DACH1 functions as tumor suppressor in NSCLC and many other cancers 23-25." (PMID 35069900, 2022). "Human Dachshund homolog 1 (DACH1) is usually defined as a tumor suppressor, which plays an influential role in tumor growth and metastasis in a variety of cancer cells." (PMID 34772908, 2021). "It has been demonstrated that dachshund homolog 1 (DACH1) was a tumor suppressor in progestin-resistant Ishikawa PR EC cells because its overexpression was able to inhibit EMT and reverse drug resistance." (PMID 35582386, 2021). "Previous reports have shown the tumor suppressive roles of DACH1, PCDH10 and SMAD4 in tumorigenesis 24-26." (PMID 33867818, 2021). "Downregulated genes like DACH1 are also downregulated in both zebrafish and multiple tumor entities." (PMID 33362851, 2020). "DACH1 expression was reduced or lost in invasive breast cancer patients with a poor prognosis, with its expression inversely related to tumor diameter, stage, and nodal metastasis, and directly associated with increased survival time." (PMID 33378353, 2020). "We examined the clinical attributes of the cancers by DACH1 status by comparing whole-exome sequencing (WES), RNA Sequencing (RNASeq), microsatellite instability (MSI), and tumor mutational burden (TMB)." (PMID 33378353, 2020). "The results showed that DACH1 level in tumor tissues was significantly lower than normal tissues (P < 0.05)." (PMID 32550045, 2020). "IHC staining was performed to evaluate the protein level of DACH1, CXCL1, cyclin D1, and Ki67 in nude mice xenograft tumor tissues from cells expressing vector control and DACH1." (PMID 31998654, 2019). "Functional studies identified DACH1 as a tumor suppressor in several cancer types, such as breast cancer, colorectal cancer, and renal cell carcinoma, and so on." (PMID 31998654, 2019). "Taken together, these in vivo results indicate that knockdown of DACH1 promotes tumor growth of EC and MPA resistance." (PMID 31215145, 2019). "The tumor tissues isolated from those nude mice were further immunized with four antibodies: DACH1, CXCL1, cyclin D1, Ki67." (PMID 31998654, 2019). "DACH1 has been considered as a tumor suppressor and represses the expressions of several chemokines." (PMID 31998654, 2019). "Immunohistochemical staining of xenograft tumor tissues was conducted to evaluate the protein abundance of DACH1, cyclin D1, Ki-67, and CXCL8 in DACH1-overexpressed and control tumors." (PMID 29636079, 2018). "TIC or CSC is a stem cell that facilitates tumor initiation, however, re-expression of DACH1 decreased the tumor and mammosphere formation, reduced the CD44high/CD24low proportion in BTIC, and repressed the expression of Sox2, Oct4, Nanog, KLF4 and c-Myc." (PMID 30261897, 2018).